LDOC1 (LDOC1 regulator of NFKB signaling)
Diseases named in the same sentence as LDOC1 in open-access papers (continued):
Sharing a sentence is not in itself a finding about the gene and the disease.
thyroid (1 paper, 2015). "In summary, this study highlights the functionality of LDOC1 in thyroid carcinogenesis." (PMID 26637328, 2015).
thyroid cancer (1 paper, 2015). "Taken together, these data suggest that LDOC1-mediated NF-κB inhibition markedly sensitized the TPC-1 thyroid cancer cells to apoptosis in response to extracellular stimulation." (PMID 26637328, 2015). "Furthermore, we found that LDOC1 expression sensitizes thyroid cancer cells to apoptosis by suppressing both basal and TNFα-induced activation of NF-κB signaling, and, consequently, increases the responsiveness of these cells to TGF-β1 inhibitory signaling." (PMID 26637328, 2015). "We demonstrated that LDOC1 is downregulated in PTC tumor tissues and in thyroid cancer cell lines (BCPAP and TPC-1), and that LDOC1 expresion is relevant to tumor size and nuclear P65 content in PTC tissues." (PMID 26637328, 2015).
vulvar intraepithelial neoplasia (1 paper, 2020). Intraepithelial neoplasia of the vulvar squamous epithelium. "In normal vulvar tissue, no expression of LDOC1 was shown, whereas moderate cytoplasmatic expression of LDOC1 could be detected in vulvar intraepithelial neoplasia." (PMID 33291445, 2020).
cancer (19 papers, 2008 to 2024). A tumor composed of atypical neoplastic, often pleomorphic cells that invade other tissues. "This supports our finding that promoter hypermethylation plays a causative role in LDOC1 silencing in human cancers." (PMID 30634502, 2019). "The methylation status of LDOC1 could potentially provide a molecular marker for the screening of smokers at high risk of cancer." (PMID 26317789, 2015). "We have previously demonstrated that LDOC1 functions as a tumor suppressor gene in two EGFR-driven cancers: oral squamous cell carcinoma and NSCLC." (PMID 38338651, 2024). "In cancer conditions, LDOC1 expression is downregulated and GNL3L ultimately enhances NF-κB activity by regulating phosphorylation levels and stability of the NF-κB p65 subunit and IκB." (PMID 39682774, 2024). "To further explore the molecular mechanisms of LDOC1, we examined the expression of essential proteins in the AKT/mTOR signaling pathway implicated in cancer cell viability and proliferation." (PMID 35957693, 2022). "LDOC1 deficiency leads to enhanced IL-6/JAK2/STAT3 loop, through which LDOC1 mediates cancer progression." (PMID 36591515, 2022). "LDOC1 was expressed by about 90% of the cancer cells in the cytoplasm and about half of the cells in the nucleus." (PMID 33291445, 2020). "The leucine zipper downregulated in cancer 1 gene (LDOC1) has been identified in various carcinomas as a tumor-relevant protein influencing patients’ survival and prognosis." (PMID 33291445, 2020). "In these human cancers, LDOC1 functions as a tumor suppressor by inhibiting proliferation and metastasis and by inducing apoptosis." (PMID 30634502, 2019). "LDOC1 is widely expressed in a variety of normal human tissues but is decreased in various human cancers." (PMID 31889905, 2019). "We found that LDOC1 deficiency led to reinforcing a reciprocal loop of IL-6/JAK2/STAT3, through which LDOC1 mediates the cancer progression." (PMID 30634502, 2019). "The literatures provided evidence of both upregulation and downregulation of LDOC1 resulting in cancer." (PMID 30993049, 2019). "Several cancer studies have reported hypermethylation in the LDOC1 promoter region, and that LDOC1 silencing is associated with a history of cigarette smoking." (PMID 30993049, 2019). "Although LDOC1 is ubiquitously expressed in all tissues but downregulated or silenced in many cancer types—including cervical cancer, ovarian cancer, OSCC, papillary thyroid carcinoma, and osteosarcoma." (PMID 30634502, 2019). "LDOC1 (leucine-zipper down-regulated in cancer) is a tumour suppressor gene that is expressed in most normal tissue, but lost in some cancers." (PMID 26781748, 2016). "Lastly the human LDOC1/MART7 gene was found ubiquitously expressed in human tissues and down regulated in some cancer cell lines." (PMID 25888968, 2015). "In summary, our findings not only strengthen the association between cigarette smoke and altered epigenome in OSCC, they also suggest a critical role of LDOC1 in other tobacco-related cancers." (PMID 26317789, 2015). "In contrast, LDOC1/MART7 showed down regulation of expression in carcinoma cells, supporting possible tumor suppressor activity." (PMID 25888968, 2015). "In fact, WAVE3 was reported to negatively regulate the activity of LDOC1, the function of which is to inhibit NFκB activation and to sensitize cancer cells to apoptosis." (PMID 25329315, 2014). "ECRG4 and LDOC1 were selected for further analysis based on their putative function as tumor suppressor genes in other cancer types." (PMID 23185447, 2012). "Genes encoding for proteins TPRKB, T-Complex 1 (TCP1), Olftactomedin 1 (OLFM1), LDOC1 and HTRA3 have been implicated positive or negatively in cancer progression." (PMID 18793431, 2008). "Several studies have also reported the molecular mechanism by which LDOC1 regulates cancer cells." (PMID 35957693, 2022).
cancer (continued). "Accordingly, we proposed that the Akt/GSK-3β axis may be involved in the LDOC1-mediated suppression of IL-1β production and anti-cancer effects in OSCC." (PMID 33120999, 2020). "There has been evidence that microRNAs could modulate drug-resistant genes, thereby playing important roles in chemosensitivity, and the GNL3L gene can be affected by LDOC1, but this gene is mostly hypermethylated in cancers." (PMID 32422901, 2020). "Here, LDOC1 is inhibited by hsa-miR-155 and ultimately drives cancer cell growth." (PMID 31889905, 2019). "To examine the expression of LDOC1 protein in oral malignant transformation, we carried out immunohistochemistry study with tissue microarrays containing oral biopsies covering normal, precancerous lesions, and all stages of cancer progression." (PMID 26317789, 2015). "Furthermore, LDOC1 has been described to regulate NF-κB activation in human cancer cells and biliary epithelial cells." (PMID 26637328, 2015). "The WAVE3-mediated modulation of NFκB activity and apoptosis could also be exerted through its regulation of the LDOC1 protein, (a leucine zipper protein that is down-regulated in cancer cells)." (PMID 25329315, 2014). "Moreover, proliferation, cell-cycle progression, and invasiveness of cancer cells may be regulated by LDOC1 through distinct signaling pathways." (PMID 30634502, 2019). "On the other hand, it has been suggested that the downregulation of LDOC1 and HTRA3 genes may play an important role in the development and/or progression of some cancers." (PMID 18793431, 2008). "Thus, LDOC1 might serve as a promising novel biomarker and therapeutic target for the diagnosis and treatment of PTC and other cancers." (PMID 26637328, 2015).
tumor (16 papers, 2012 to 2026). "Our previous study identified leucine-zipper downregulated in cancer 1 (LDOC1), as an X-linked tumor suppressor in OSCC." (PMID 33120999, 2020). "Our previous study revealed global epigenetic aberrations in smoking-associated OSCC patients, and identified BEX1 and LDOC1 as 2 X-linked tumor suppressor genes with promoter methylated in 75% and 89% of OSCC tumor samples, respectively." (PMID 26317789, 2015). "Moreover, sex-specific environmental mechanisms can mediate the loss of LDOC1 function as a tumor suppressor." (PMID 33291445, 2020). "In another study, we identified LDOC1 as an X-linked tumor suppressor and revealed that it is frequently silenced by promoter hypermethylation in oral squamous cell carcinoma (OSCC) in patients who habitually drink alcohol, chew betel quid, or smoke cigarettes." (PMID 30634502, 2019). "Leucine Zipper, Down-regulated in Cancer-1 (LDOC1) is an X-linked tumor suppressor gene." (PMID 30993049, 2019). "For the IHC results, only nine of 31 HCC tumor tissue showed medium and high expression of LDOC1, whereas 24 of 31 paracancerous tissues showed significant positive LDOC1." (PMID 35957693, 2022). "In this study, we aimed to investigate how LDOC1 influenced tumor progression and the biological functions of HCC." (PMID 35957693, 2022). "Downregulation of LDOC1 was discovered in various tumor tissues, such as the lung, colorectum, cervix, vulva, pancreas, and papillary thyroid." (PMID 35957693, 2022). "LDOC1 is an important tumor-suppressor gene that mainly contributes to the regulation of transcriptional response mediated by the nuclear factor kappa B." (PMID 32528944, 2020). "In this study, we focused on leucine zipper downregulated in cancer 1 (LDOC1), a tumor suppressor candidate gene that was discovered for the first time to be downregulated in pancreatic and gastric cancer cells." (PMID 33291445, 2020). "Here, we also observed that the reduction in LDOC1 mRNA levels was associated with an increase in the size of primary PTC tumors, and that LDOC1 mRNA was almost undetectable in certain specimens in which the tumor size was >4 cm." (PMID 26637328, 2015). "The expression levels of LDOC1 were lower with tumor grade progression." (PMID 35957693, 2022). "LDOC1 showed tumor-suppressed effects in several tumor cells." (PMID 35957693, 2022). "In summary, our findings suggest that LDOC1 may have tumor-suppressive effects by inhibiting AKT/mTOR activation in HCC." (PMID 35957693, 2022). "Whether the expression of LDOC1 in the tumor attracts mainly macrophages, or whether the tumor suppressor LDOC1 is expressed independently in the immune cells, must be investigated in following experiments." (PMID 33291445, 2020). "In the setting of LDOC1 silencing, oral microorganisms such as CA and FN may become pro-tumor through stimulating production of oncogenic IL-1β." (PMID 33120999, 2020). "Given the potential interaction with basic leucine-zipper transcription factors (TFs), we speculated that LDOC1 exerts a tumor suppression function through transcriptional regulation." (PMID 30634502, 2019). "In addition to modulating tumor biology in several human malignancies, LDOC1 participates in innate immune response and homeostasis of the intestinal mucosa." (PMID 30634502, 2019). "LDOC1 expression was significantly downregulated in PTC specimens as compared with the expression in normal thyroid tissues, and this downregulation was associated with an increase in tumor size (P < 0.05)." (PMID 26637328, 2015). "Tumor growth could be inhibited by C-DIM 12 in vitro if the expressed LDOC1 level was high enough." (PMID 33291445, 2020). "Therefore, we concluded that LDOC1 might act as a tumor suppressor gene in HCC." (PMID 35957693, 2022). "We have shown increased expression of metastasis markers CXCR4, SDF-173,74 and decreased tumor suppressor molecules LDOC1 and FOXO3, induction of oncogenes and promotion of tumor growth." (PMID 30413788, 2018).
tumor (continued). "The results delineate increased expression of angiogenic and oncogenic markers CXCR4, SDF-1, and decreased expression of tumor suppressor genes, IRF1, LDOC1, and FOXO3 in CP patient tissues." (PMID 30413788, 2018). "In this study, we validated the downregulation of LDOC1 in human PTC tissue samples and its relationship to tumor size and nuclear p65 content." (PMID 26637328, 2015). "mRNA expression of the candidate genes MEIS1, LDOC1, AGTR1, BAK1, TYMS and DTL were analyzed in 3 cell lines (Hep2, KB and SCC 084), 1 primary HNSCC tumor and 3 normal head and neck tissue samples." (PMID 25186767, 2014). "The LDOC1-H2Bub1 axis, potentially involving THAP12, shapes chromatin accessibility and metastatic transcriptional programs, providing mechanistic and clinical insights into tumor aggressiveness and therapeutic response." (PMID 41484780, 2026). "In contrast to the LDOC1-positive area of the tumor, LDOC1-positive infiltrating immune cells did not have any influence on the patients’ outcome." (PMID 33291445, 2020). "Through a literature survey, we identified that GPX3, LDOC1, LXN, and UCHL1, but not LIPG, have been reported as tumor suppressor genes, and that their expression was mediated by promoter DNA methylation." (PMID 26317789, 2015).
infection (2 papers, 2015 to 2018). The state of being infected such as from the introduction of a foreign agent such as serum, vaccine, antigenic substance or organism. "miR-296-3p and miR-744 was decreased more than 5-fold in both breeds, and they could target LDOC1 (up-regulated post-infection), which served as a negative regulator of NF-κB32 and was involved in anti-inflammatory response in both two breeds." (PMID 30353051, 2018).
LDOC1 also shares sentences with these, for which no sentence is quoted: colorectal cancer (2 papers); pancreatic cancer (2); small cell lung carcinoma (2); acute myeloid leukemia (1); autism spectrum disorder (1); benign tumors (1); Bovine mastitis (1); breast carcinoma (1); chronic lymphocytic leukemia (1); diabetes (1); dysplasia (1); esophageal adenocarcinoma (1); head and neck cancer (1); leukemia (1); lung squamous cell carcinoma (1); mastitis (1); non-small cell lung carcinoma (1); pancreatic ductal adenocarcinoma (1); prostate (1); prostate carcinoma (1); schizophrenia (1).